IL6 (interleukin 6)
Diseases named in the same sentence as IL6 in open-access papers (continued):
Sharing a sentence is not in itself a finding about the gene and the disease.
Myocardial fibrosis (continued). "In anisoproterenol-induced myocardial fibrosis model of VMC, the lncRNA RORupregulated c-myc expression and increased serum IL-6 levels, therebyfacilitating the proliferation and differentiation of CFs." (PMID 39077397, 2023). "IL-6 levels in patients with left ventricular diastolic dysfunction (LVDD) were found to be substantially linked with the levels of fibrotic parameters, suggesting that IL-6 may play a role in increasing myocardial fibrosis and LV remodeling, finally leading to LVDD." (PMID 35997998, 2023). "Cell releases IL-6 and TNF- α can induce the decline of myocardial cell vitality and apoptosis, accelerate the secretion of a large amount of collagen and myocardial fibrosis in myocardial tissue, damage myocardial function." (PMID 37986153, 2023). "IL-6 thus functions as a down-stream signal for Cad-11 to activate MAPKs and CaMKII-STAT3 signaling pathways in the pathogenesis of myocardial fibrosis and cardiomyocyte hypertrophy." (PMID 37047522, 2023). "Cytokines, including proinflammatory signaling IL-1β, IL-6, TNF-α, and myocardial fibrosis signaling TGF-β, were significantly reduced in the BZ." (PMID 35571187, 2022). "Based on the previous studies and the present study, we suggest that the effect of ivabradine on myocardial fibrosis is related to the reduction of the proinflammatory cytokines TNF-α, IL-1β, and IL-6." (PMID 27847478, 2016). "In summary, BYHWD exerts anti-inflammatory effects by down-regulating the expression of inflammatory factors such as IL-6, IL-1β, IL-18, and NLRP3, and inhibiting the JAK/STAT and TLR4/NF-κB signaling pathways, thereby slowing down the process of myocardial fibrosis." (PMID 40881586, 2025). "This disruption is associated with elevated activity in pro-inflammatory pathways, such as JAK-STAT, NF-κB, and MAPK, alongside alterations in IL-6 and TGF-β2, which may contribute to myocardial fibrosis and hypertrophy in HCM." (PMID 40535153, 2025). "IL-6 and heat shock protein 90 (Hsp90) synergistically activate the signal transduction and transcriptional activator 3 (STAT-3) signaling pathway, leading to excessive collagen synthesis and contributing to the development of myocardial fibrosis." (PMID 40881586, 2025). "MG-EWE inhibits CF transdifferentiation and IL-6 production via the ADRB2/JNK/c-Jun signaling axis, mediated by its constituents Laurolitsine and Hecogenin, highlighting its potential for drug development targeting myocardial fibrosis." (PMID 41150746, 2025). "The inflammatory cascade reaction mediated by neutrophil granulocyte and mononuclear macrophages is one of the common mechanisms leading to the myocardial fibrosis, which can secrete a variety of proinflammatory cytokines such as TNF-α, IL-1β, and IL-6, leading to the myocardial fibrosis." (PMID 36105253, 2022). "Activated B cells promote cytokine (TNF-α, IL-1β, IL-6, TGF-1β) secretion and may participate in the pathological process of myocardial injury after AMI, which is related to myocardial fibrosis after AMI." (PMID 33407160, 2021). "The results showed that B-cell deletion reduced the expression of the cytokines TNF-α, IL-1β, IL-6, and TGF-1β, decreased myocardial collagen synthesis after AMI, alleviated myocardial fibrosis, improved left ventricular remodelling, and maintained the left ventricular ejection fraction." (PMID 33407160, 2021). "NF-κB contributes to myocardial fibrosis pathogenesis because it regulates genes/proteins important for disease progression, including cytokines (e.g., TNF-α), interleukins (e.g., IL-6), growth factors (e.g., TGF-β), and adhesion molecules (e.g., intercellular adhesion molecule)." (PMID 24171042, 2013). "Given the critical role of CFs activation in the pathogenesis of myocardial fibrosis, the present study was designed to investigate the molecular mechanisms through which MG-EWE and its bioactive constituents influence CFs transdifferentiation and IL-6 production." (PMID 41150746, 2025).
Myocardial fibrosis (continued). "Furthermore, the experimental results suggested that GZD could downregulate the expression levels of IL-6, IL-1β, CCL2, MMP-2, and MMP-9, thus inhibiting the inflammation and myocardial fibrosis in Dahl salt-sensitive rats." (PMID 33906674, 2021). "Additionally, studies have shown that the increase in immune cell infiltration and inflammatory cytokines such as tumor necrosis factor-α (TNF-α) and interleukin-6 (IL-6) in the myocardial tissue of HCM patients may contribute to the development and progression of myocardial fibrosis in HCM." (PMID 40271123, 2025).
AIDS (118 papers, 2007 to 2026). A syndrome resulting from the acquired deficiency of cellular immunity caused by the human immunodeficiency virus (HIV). "Some studies have also demonstrated associations between the high level of circulating IL-6 and various clinical outcomes, including death and the onset of acquired immune deficiency syndrome." (PMID 30611204, 2019). "Clinical studies revealed that the serum concentration of low-density lipoproteins positively correlate with IL-6 in acquired immune deficiency syndrome (AIDS) patients infected with human immunodeficiency virus (HIV)." (PMID 30249998, 2018). "Inflammatory factors such as tumor necrosis factor- α (TNF-α) and interleukin-6 (IL-6) are elevated in patients with HIV infection/AIDS, strongly suggesting a possible association between disease progression and inflammatory response." (PMID 40217405, 2024). "Tumor necrosis factor (TNF) and interleukin 6 (IL-6) represent pro-inflammatory cytokines associated with AIDS progression and were quantified using a cytometric bead array." (PMID 39459974, 2024). "High levels of IL-6 have been described as a potential biomarker for TB and are associated with higher plasma viral loads and faster progression to AIDS in several studies." (PMID 36204643, 2022). "IL-6 inhibitors have also been proposed as a treatment option for rare and severe AIDs such as vacuoles, E1 enzyme, X-linked, autoinflammatory, somatic (VEXAS) syndrome caused by somatic variants in the UBA1 gene." (PMID 35958618, 2022). "Of note, monocyte activation with increased release of IL-6 has repeatedly been reported to be associated with non-AIDS-defining events, immune aging and all-cause mortality in patients on antiretroviral therapy." (PMID 33278000, 2021). "In a study involving macaques with SIV-induced encephalitis, rapid progression to Acquired Immune Deficiency Syndrome (AIDS) correlated with an increase in IL-1β, IL-2, IL-6, IL-10, and TNF-α." (PMID 34784367, 2021). "Prospective results in HIV+ patients have found high serum levels of IL-6 and IL-10 that progressively increased during the years before the diagnosis of AIDS-associated B-cell lymphoma." (PMID 30337929, 2018). "Markers of systemic inflammation (hsCRP, interleukin 6 (IL6)) and coagulation (D-dimer) have been associated with all-cause mortality, non-AIDS illnesses (NAI) and more specifically cardiovascular disease (CVD) in PLWH." (PMID 29443936, 2018). "In joint models, IL-6 and D-dimer were independently associated with serious non-AIDS conditions or death, with consistent results across the 3 cohorts and across serious non-AIDS event types." (PMID 27171281, 2016). "Both IL-6 and D-dimer are independently associated with serious non-AIDS conditions or death among HIV-positive adults with suppressed virus." (PMID 27171281, 2016). "In summary, both IL-6 and D-dimer independently predict the risk of serious non-AIDS conditions or death among HIV-positive patients with suppressed virus and moderate to high CD4 cell counts." (PMID 27171281, 2016). "IL-6, D-dimer and hsCRP were each individually associated with risk of serious non-AIDS conditions or death, HR = 1.45 (95% CI: 1.30 to 1.63), 1.28 (95% CI: 1.14 to 1.44), and 1.17 (95% CI: 1.09 to 1.26) per 2x higher biomarker levels, respectively." (PMID 27171281, 2016). "For 25% lower “usual” IL-6 and D-dimer levels, the joint biomarker model estimates a 37% reduction (95% CI: 28 to 46%) in the risk of serious non-AIDS conditions or death if the relationship is causal." (PMID 27171281, 2016). "The association of IL-6 and D-dimer with serious non-AIDS conditions or death was graded and persisted throughout follow-up." (PMID 27171281, 2016). "In HIV-positive adults on suppressive ART, associations of IL-6, D-dimer, and hsCRP levels at study entry with serious non-AIDS conditions or death were studied using Cox regression." (PMID 27171281, 2016).
AIDS (continued). "Hazard ratios (HR) adjusted for age, gender, study, and regression dilution bias (due to within-person biomarker variability) were used to predict risk reductions in serious non-AIDS conditions or death associated with lower “usual” levels of IL-6 and D-dimer." (PMID 27171281, 2016). "In addition, IL-6 has recently been implicated as a predictor of clinical events, serious non-AIDS conditions (SNA) and death in HIV patients." (PMID 34640478, 2021). "While both IL-6 and D-dimer have been shown to be independently associated with serious non-AIDS conditions or death among HIV-positive adults with suppressed virus, posing them as ideal biomarkers for interventional strategies, hs-CRP involvement as correlate of disease progression is less clear." (PMID 34116650, 2021). "On the other hand, there are studies that reported IL-6 to be strongly associated to non AIDS events compared to CRP during HIV infection, therefore variability observed in our study may be due to chance." (PMID 31331321, 2019). "It has been reported that acquired immune deficiency syndrome patients with decreased levels of DHEA-S show excessive cytokine production by Th2 cells (IL-4, IL-5, IL-6, and IL-10) and suppression of other cytokines (IL-2, IFN-γ, IL-12)." (PMID 29694639, 2018). "Furthermore, clinically significant elevations in SAA were associated with IL-6 and IL-8 levels and these have been previously reported to be associated with serious non-AIDS events." (PMID 25888119, 2015). "Elevated levels of pro-inflammatory cytokines like IL-6, IL-1β, and TNF-α are associated with an increased risk of non-AIDS-related comorbidities such as cardiovascular diseases, neurocognitive disorders, and certain cancers." (PMID 40184131, 2025). "The SMART trial was the first randomized study to link persistent inflammation and coagulation by measuring interleukin 6 (IL-6) and D-dimers to an increase in non-AIDS–defining illnesses in treated individuals with HIV-1." (PMID 39226296, 2025). "Patients with AIDs often have elevated levels of pro-inflammatory cytokines such as tumor necrosis factor-α, IL-1, IL-6, and chemokines in their bloodstream." (PMID 41239630, 2025). "The increased production of cytokines such as IL-6, IL-1 and TNF-alpha in monocytes is associated with non-AIDS comorbidities in PLWHIV." (PMID 40331967, 2025). "IL-6 is reduced in plasma of individuals with AIDS, and this is related to fungemia and dissemination." (PMID 39334365, 2024). "Low IL-6 levels in CSF are correlated with reduced survival in patients with HIV/AIDS and cryptococcal meningoencephalitis." (PMID 39334365, 2024). "Chronic inflammation (eg, elevated IL-6 and type I IFNs) and microbial translocation from a compromised mucosa are central to the pathogenesis of non-AIDS comorbidities in PWH on suppressive ART." (PMID 39635460, 2024). "Tocilizumab, an IL-6 blocking biologic, showed efficacy in sJIA and is currently being repositioned for use in the treatment of AIDs, but its efficacy in AID is lower than that of IL-1 blockers." (PMID 38034538, 2023). "In this study, we were interested in measuring IL-6Rα in EVs as IL-6 levels are significantly elevated in HIV-infected individuals years prior to an AIDS-NHL diagnosis." (PMID 37809067, 2023). "The use of IL-6 inhibitors as a second-line therapy in patients with monogenic AIDs, such as familial Mediterranean fever and TRAPS, has been described." (PMID 38034538, 2023). "Chronic systemic inflammation (higher sCD14, IL-6 and D-dimer levels) is associated with increased risk of worse HIV disease outcomes and serious non-AIDS events." (PMID 35511802, 2022). "A recent clinical trial indicated a higher level of IL-6 in AIDS-Kaposi’s sarcoma group compared to HIV individuals." (PMID 36032099, 2022). "Of these, TNF-α, IL-6, IL-8 and IP10 are associated with prognoses in patients with HIV/AIDS cryptococcal meningitis and IL-6 is also involved in anticryptococcal drug resistance." (PMID 36310879, 2022).
AIDS (continued). "Serum IL-6/IL-10 ratio was also used to evaluate the severity of pneumocystis pneumonia in HIV/AIDS patients." (PMID 36371539, 2022). "We have briefly reviewed the role of IL-6 in AIDs and considered the pros and cons of IL-6 inhibitors as a treatment for AIDs." (PMID 35958618, 2022). "Inflammation is associated with untreated HIV-1 infection, and high baseline levels of IL-6, IL-10, and TNF-α are associated with increased risks of AIDS-defining events." (PMID 34983415, 2022). "A SNP screening in AIDS‐KS patients including several cellular homologues identified SNPs in CCND1, IL6, CCL2 and CFLAR (homologues of KSHV‐encoded vCyclin, vIL6, viral FLICE‐inhibitory protein (vFLIP) and viral CC chemokine ligand (vCCL), respectively)." (PMID 33043529, 2021). "In TB, IL-6 was the highest by the Youden index of 1.698, and the only AIDS/TB candidate MIP-1β showed a Youden index of 1.764." (PMID 33143141, 2020). "On the other hand, the Th2-specific cytokines, i.e., IL-4, IL-5, IL-6, IL-10, and IL-13, are associated with disease progression and lead to the progression of HIV infection to AIDS." (PMID 31641392, 2019). "There were four markers that inversely associated with AIDS-KS sGP130 (OR=0.14; CI= 0.03, 0.73; p=.0197), BAFF (OR=.60; CI=.16.90p=.0282), sCRP (OR=.61; CI=.43.87; p=.0064) and IL-6 (OR=.51; CI= .35.76; p=.0009)." (PMID 33521162, 2018). "Decreased levels of IL-6 and its downstream targets, sGP130 and sCRP, as well as BAFF, correlated with a greater risk of AIDS-KS." (PMID 33521162, 2018). "During HIV chronic infection, the presence of IL-6, IL-10, and TNF-α are associated with poor prognosis and progression to AIDS because they contribute to the chronic activation of B-cells." (PMID 30337929, 2018). "Recently, persistent inflammation characterised e.g. by increased IL-6 serum concentrations from AIDS patients were found to correlate with T-cell exhaustion/senescence and impaired T-cell response to IL-7." (PMID 28582466, 2017). "Chronic inflammation and increased serum concentrations of IL-6 were found in HIV/AIDS, and functional in vitro assays indicated inhibitory effects of the pro-inflammatory cytokines IL-6 and IL-1β on IL-7-mediated signal transduction." (PMID 28582466, 2017). "Chronic inflammation and increased IL-6 serum concentrations were found in AIDS patients with impaired T-cell immunity to IL-7." (PMID 28582466, 2017). "In this study, we established a PBL cell line from a case of AIDS-associated PBL, and demonstrated its interleukin 6 (IL-6)-dependent growth." (PMID 28860565, 2017). "We have observed significant association between elevated levels of IL-6 and CRP among the AIDS Linked to the Intra Venous Experience (ALIVE) study participants, a large cohort of injection drug users (IDUs) with or at high risk for HIV infection." (PMID 29097998, 2017). "In conclusion, our data suggest that detection of plasma IL-8 levels and IL-6/IL-10 ratio combined with LDH and HBDH can predict the severity of PCP risk of death in AIDS patients with PCP." (PMID 27579328, 2016). "Accordingly, during the course of HIV-1 infection, an increase in the production of pro-inflammatory cytokines, including TNF-α, IL-1β, IL-6 and IL-8, is associated with the activation of HIV-1 viral replication, and the progression to AIDS." (PMID 26090662, 2015). "Long term follow up of the SMART and ESPRIT study cohorts, two large international cohorts with almost 10,000 participants, identified smoking and elevations in IL-6 and D-dimer as significant predictors of death, AIDS and significant non-AIDS events." (PMID 26641655, 2015). "High-sensitivity C-reactive protein (hsCRP) and Interleukins 6 and 10 (IL-6, IL-10) have been reported as predictors of serious non-AIDS defining events including CVD, cancer and overall mortality." (PMID 25888119, 2015).